PNPLA8 (patatin like domain 8, phospholipase A2 )
Description:
Calcium-independent and membrane-bound phospholipase, that catalyzes the esterolytic cleavage of fatty acids from glycerophospholipids to yield free fatty acids and lysophospholipids, hence regulating membrane physical properties and the release of lipid second messengers and growth factors. Hydrolyzes phosphatidylethanolamine, phosphatidylcholine and probably phosphatidylinositol with a possible preference for the former. Also has a broad substrate specificity in terms of fatty acid moieties, hydrolyzing saturated and mono-unsaturated fatty acids at nearly equal rates from either the sn-1 or sn-2 position in diacyl phosphatidylcholine. However, has a weak activity toward polyunsaturated fatty acids at the sn-2 position, and thereby favors the production of 2-arachidonoyl lysophosphatidylcholine, a key branch point metabolite in eicosanoid signaling. On the other hand, can produce arachidonic acid from the sn-1 position of diacyl phospholipid and from the sn-2 position of arachidonate-containing plasmalogen substrates. Therefore, plays an important role in the mobilization of arachidonic acid in response to cellular stimuli and the generation of lipid second messengers. Can also hydrolyze lysophosphatidylcholine. In the mitochondrial compartment, catalyzes the hydrolysis and release of oxidized aliphatic chains from cardiolipin and integrates mitochondrial bioenergetics and signaling. It is essential for maintaining efficient bioenergetic mitochondrial function through tailoring mitochondrial membrane lipid metabolism and composition.
Synonyms: IPLA2G; IPLA2-2; iPLA2gamma; MMLA; PNPLA-gamma
Tractability: Antibody: UniProt predicts a signal peptide or a membrane-spanning region. PROTAC: ubiquitination databases record sites on it; its protein half-life has been measured.
Target class: Enzyme; Hydrolase
Gene: Protein-coding gene on chromosome 7 (108,470,417 to 108,569,666, reverse strand). Ensembl gene ENSG00000135241.
Subcellular location: Endoplasmic reticulum membrane; Mitochondrion membrane; Peroxisome membrane
Subcellular location (Human Protein Atlas): Cytosol; Nucleoplasm; Golgi apparatus
Pathways (Reactome):
Metabolism: Acyl chain remodelling of PC; Acyl chain remodelling of PE
Gene Ontology:
Molecular function: phosphatidylcholine lysophospholipase activity; phospholipase A2 activity; ATP binding; phospholipase A1 activity; phospholipase activity
Biological process: arachidonate metabolic process; arachidonate secretion; cardiolipin metabolic process; fatty acid metabolic process; intracellular signal transduction; linoleic acid metabolic process; lipid homeostasis; phosphatidylcholine catabolic process; phosphatidylethanolamine catabolic process; prostaglandin biosynthetic process; triglyceride homeostasis; lipid metabolic process; regulation of cellular response to oxidative stress
Cellular component: membrane; mitochondrion; peroxisomal membrane; peroxisome; endoplasmic reticulum membrane; mitochondrial membrane
Genetic constraint (gnomAD): Loss-of-function variants: 21 observed, 39.03 expected, observed/expected ratio (o/e) 0.54, 90% interval 0.38 to 0.77. The upper end of that interval is the gene's LOEUF score, 0.77, which puts it in group 3 of 6, group 1 being the genes least tolerant of losing a copy. Missense variants: 559 observed, 577.28 expected, observed/expected ratio (o/e) 0.97, 90% interval 0.9 to 1.04. Synonymous variants: 190 observed, 192.03 expected, observed/expected ratio (o/e) 0.99, 90% interval 0.88 to 1.12.
Gene-disease validity (ClinGen):
ClinGen rates the evidence that PNPLA8 causes each of these diseases.
mitochondrial disease (autosomal recessive): Definitive.
Homologues: Orthologues: chimpanzee PNPLA8 (99% identical), macaque PNPLA8 (97% identical), guinea pig PNPLA8 (88% identical), pig PNPLA8 (87% identical), rabbit PNPLA8 (87% identical), rat Pnpla8 (83% identical), mouse Pnpla8 (82% identical), tropical clawed frog pnpla8 (56% identical), zebrafish pnpla8 (48% identical), Caenorhabditis elegans ipla-6 (25% identical).
Diseases named in the same sentence as PNPLA8 in open-access papers:
PNPLA8 is named in the same sentence as 48 diseases in open-access papers, as found by Europe PMC text mining. Sharing a sentence is not in itself a finding about the gene and the disease. The quoted sentences say what the papers report.
cardiomyopathy (3 papers, 2023 to 2025). A disease of the heart muscle or myocardium proper. "Twelve of the 52 mouse models identified with cardiomyopathy (Acadv1, Fxn, Mto1, Taco1, Hmgcs2, Mpv17, Opa1, Pnpla8, Tmem126b, Gpd2, Mpv17, Micu1) showed that the presence of cardiomyopathy can be dependent on the degree of stress." (PMID 37103033, 2023).
Hepatic steatosis (3 papers, 2016 to 2025). Steatosis is a term used to denote lipid accumulation within hepatocytes. "Moreover, we show that over-expression of PNPLA8 dramatically decreases hepatic steatosis through increased autophagy in hepatocytes of HFD-fed mice." (PMID 27767079, 2016).
lactic acidosis (2 papers, 2023 to 2024). Metabolic acidosis characterized by the accumulation of lactate in the body. "Biallelic pathogenic variants in PNPLA8 gene have been recently associated with a severe mitochondrial neurodegenerative disease in children, manifesting with microcephaly, hypotonia, weakness, epilepsy, global developmental delay, poor weight gain, and lactic acidosis." (PMID 37784170, 2023). "In addition, two patients were found to have a PNPLA8 gene mutation, which causes mitochondrial myopathy with lactic acidosis, and it was not reported previously with PFA34." (PMID 38600369, 2024).
microcephaly (2 papers, 2020 to 2023). A congenital or acquired developmental disorder in which the circumference of the head is smaller than normal for the person's age and sex. "Recessive variants in PNPLA8 give rise to microcephaly, spasticity, cerebellar and brainstem atrophy, seizures, and muscle weakness." (PMID 33426505, 2020).
Mitochondrial myopathy (2 papers, 2016 to 2024). "Recently, mutations in human PNPLA8 identified in a young girl with a suspected mitochondrial myopathy." (PMID 26741492, 2016).
myocardial ischemia (2 papers, 2022). A disorder of cardiac function caused by insufficient blood flow to the muscle tissue of the heart. "In a mouse model of myocardial ischemia, the levels of potential lipid mediators, including eicosanoids and lysophospholipids were altered in PNPLA8-deficient and PNPLA8-overexpressing mice, suggesting that PNPLA8 also has a function in the production of these lipid mediators." (PMID 35458682, 2022). "Similarly, the deletion of PNPLA8 in adult mouse cardiomyocytes is also protective from myocardial ischemia/reperfusion injury, although the global deletion of PNPLA8 in mice leads to various physiological defects, including growth retardation, kyphosis, muscle weakness, and glomerular injury." (PMID 36292774, 2022).
schizophrenia (2 papers, 2008 to 2021). A major psychotic disorder characterized by abnormalities in the perception or expression of reality. "Some have been reported as participants in schizophrenia and neurodegenerative diseases, such as CACNA1I and PNPLA8." (PMID 34440578, 2021).
Weaver syndrome (2 papers, 2013 to 2016). Weaver syndrome (WVS) is a rare, multisystem disorder characterized by tall stature, a typical facial appearance (hypertelorism, retrognathia) and variable intellectual disability. "Considering the expression pattern and biological functions of the corresponding gene products, they had concluded that the SNP in PNPLA8 was one of the most likely variants involved in Weaver syndrome." (PMID 26992691, 2016).
breast carcinoma (1 paper, 2023). "Our analysis of the TCGA breast cancer patient dataset revealed that PNPLA8 is associated with the PI3K and MAPK signaling pathway in breast cancer tissues." (PMID 38017485, 2023). "In the future, we will measure PC, LPC and PG species in various breast cancer tissues from patients and analyze their correlation with PNPLA8 expression to further determine their potential value in TNBC diagnosis and treatment." (PMID 38017485, 2023). "Taken together, our results show that PNPLA8 is overexpressed in breast cancer tissues and correlates with pathological classification, molecular subtype, and tumor development." (PMID 38017485, 2023). "We showed that PNPLA8 is overexpressed in breast cancer cells and tissues, especially in TNBC cells and tissues, and is essential in regulating cell viability, migration and antioxidation in TNBC cells." (PMID 38017485, 2023). "To explore crucial signaling pathways associated with PNPLA8, we performed a Gene Set Enrichment Analysis (GSEA) using the data from The Cancer Genome Atlas (TCGA) breast cancer patient dataset." (PMID 38017485, 2023). "Our results showed that higher mRNA levels of PNPLA8 in primary breast tumors were correlated with shorter relapse-free survival in breast cancer patients." (PMID 38017485, 2023). "Moreover, PNPLA8 expression levels in breast cancer tissues were higher in patients with more significant lymph node metastasis." (PMID 38017485, 2023). "PNPLA8 protein levels in breast cancer tissues are correlated with lymph node metastasis." (PMID 38017485, 2023). "The decreases of AA, PGE2 and 20-HETE in PNPLA8-silenced TNBC cells support that high PNPLA8 levels in TNBC could drive breast cancer progression through the activation of the arachidonic acid cascade." (PMID 38017485, 2023). "Our results also showed that PNPLA8 protein levels were overexpressed in HER2+ (SKBR3) and TNBC (MDA-MB-231, MDA-MB-468, SUM159P, Hs578T) breast cancer cell lines compared to other cell lines." (PMID 38017485, 2023). "We discovered that patatin-like phospholipase domain-containing lipase 8 (PNPLA8) is overexpressed in TNBC cell lines and tissues from breast cancer patients." (PMID 38017485, 2023). "Tumor tissues of the TNBC subtype showed higher PNPLA8 levels compared to luminal and HER2+ breast cancer tissues." (PMID 38017485, 2023). "Next, we performed correlation analysis of the protein levels of PNPLA8 and LPCAT4 with the detected lipid abundances in the tested panel of breast cancer cell lines, which was based on our Western Blot and lipidomic analysis results." (PMID 38017485, 2023). "In addition to PNPLA8, we also detected LPCAT4 mRNA and protein levels to be downregulated in breast cancer cell lines." (PMID 38017485, 2023). "Gene screening and TMA studies showed for the first time that PNPLA8 expression is significantly elevated in TNBC cell lines and tissues and correlated with breast cancer patient survival, pathological classification, histological grade, TNM stage and lymph node metastasis." (PMID 38017485, 2023). "Overall, the mRNA and protein expressions of PNPLA8 and LPCAT4 were consistently dysregulated in the tested panel of breast cancer cell lines, and both gene expression levels were correlated with relapse-free survival in breast cancer patients." (PMID 38017485, 2023). "However, the trends of PNPLA8 mRNA and protein levels were not consistently matched in each tested breast cancer cell line." (PMID 38017485, 2023). "In addition, PNPLA8 levels were increased in histological grade 3 (G3) breast cancer patients as compared to grade 2 (G2) patients and were also increased in TNM stage IIIB breast cancer patients as compared to stage IIB and IIA patients." (PMID 38017485, 2023).
breast carcinoma (continued). "The CPTAC breast cancer dataset also showed that PNPLA8 protein levels in TNBC were higher than those in normal breast tissues and other breast cancer subtypes, although there was no statistical significance between TNBC and other subtypes owing to insufficient sample size for the TNBC group." (PMID 38017485, 2023).
cognitive deficits (1 paper, 2013). "In mice, PNPLA8 knockouts show significant motor abnormalities and cognitive deficits over time, associated with synaptic loss and α-synuclein accumulation in brain." (PMID 23527149, 2013).
colon cancer (1 paper, 2023). "Our study revealed that silencing of PNPLA8 decreased both cellular and extracellular PGE2 levels in TNBC cell lines, which is consistent with a recent study showing that overexpression of PNPLA8 increased AA release and PGE2 production in colon cancer cells." (PMID 38017485, 2023).
colorectal cancer (1 paper, 2023). A primary or metastatic malignant neoplasm that affects the colon or rectum. "Only one study so far has shown that PNPLA8 is overexpressed in human colorectal cancer tissues and promotes azoxymethane-induced colon carcinogenesis." (PMID 38017485, 2023).
metabolic syndrome (1 paper, 2023). A cluster of metabolic risk factors for CARDIOVASCULAR DISEASES and TYPE 2 DIABETES MELLITUS. "PNPLA8 gene deficiency causes mitochondriopathy, myocadial dysfunction, neurodegeneration, metabolic syndrome and thrombosis in mice." (PMID 38017485, 2023).
triple-negative breast carcinoma (1 paper, 2023). An invasive breast carcinoma which is negative for expression of estrogen receptor (ER), progesterone receptor (PR), and human epidermal growth factor receptor 2 (HER2). "Second, we have discovered that PNPLA8 is a key master regulator of phospholipid reprogramming and eicosanoid signaling induced proliferation and migration in triple-negative breast cancer, which could be translated to the clinic as a novel diagnostic immunohistochemistry marker." (PMID 38017485, 2023).
vitiligo (1 paper, 2025). Generalized well circumscribed patches of leukoderma that are generally distributed over symmetric body locations and is due to autoimmune destruction of melanocytes. "In conclusion, PTGDS, PNPLA8, and MGLL were implicated in AAM to influence the pathogenesis of vitiligo." (PMID 40078960, 2025). "The RT-PCR results showed that compared with the control group, the expressions of PTGDS and MGLL in the skin tissues of vitiligo patients were significantly downregulated, whereas the expression of PNPLA8 was significantly upregulated." (PMID 40078960, 2025). "In this study, we first obtained six AAM-RGs in vitiligo by searching the transcriptome dataset in the GEO database along with difference analysis and machine learning; then, PTGDS, PNPLA8, and MGLL were verified as the three key genes through the validation set." (PMID 40078960, 2025). "However, the specific roles of MGLL and PNPLA8 in vitiligo are not directly reported; thus, future studies may further explore the roles of these enzymes in vitiligo and their potential clinical applications." (PMID 40078960, 2025).
neurodegenerative disease (4 papers, 2016 to 2023). A disorder of the central nervous system characterized by gradual and progressive loss of neural tissue and neurologic function. "PNPLA8 isinvolved in facilitating lipid storage in adipocyte tissue energy mobilization andmaintains mitochondrial integrity, as well as plays a role in lipid metabolismassociated with neurodegenerative diseases." (PMID 29635409, 2018).
neurological disease (3 papers, 2012 to 2020). "Weaver is a neurological disease and while NRCAM, PNPLA8, and CTTNBP2 are all expressed in nervous tissues, overall NRCAM is expressed at higher levels across all nervous tissues, including the spinal cord." (PMID 23527149, 2013).
cancer (2 papers, 2012 to 2023). A tumor composed of atypical neoplastic, often pleomorphic cells that invade other tissues. "Moreover, silencing of PNPLA8 inhibits the arachidonic acid cascade and eicosanoid production in TNBC, which may affect critical cancer cell behaviors through the PI3K/Akt/GSK3β and Mek/Erk pathways." (PMID 38017485, 2023). "The role of PNPLA8 in cancer development is not well studied." (PMID 38017485, 2023).
Tumor (2 papers, 2023). "Heatmap representation revealed that PNPLA7 and to a lesser extent PNPLA8 were markedly downregulated in tumor tissues relative to non-tumor tissues in most patients, regardless of the stage or etiology of HCC." (PMID 36979406, 2023). "In human HCC (obtained from patients who had been treated in the Hepatobiliary Pancreatic Division, Department of Surgery, the University of Tokyo Hospital), the expression levels of PNPLA7 and PNPLA8, but not PNPLA6 and PNPLA9, were significantly lower in tumor tissues than in non-tumor tissues." (PMID 36979406, 2023).
PNPLA8 also shares sentences with these, for which no sentence is quoted: Obesity (5 papers); infection (2); Insulin resistance (2); nephritis (2); non-alcoholic fatty liver disease (2); Alzheimer disease (1); Atrophy (1); brain disorder (1); brain injury (1); breast tumors (1); developmental delay (1); diabetes (1); diabetic nephropathy (1); epilepsy (1); focal segmental glomerulosclerosis (1); glomerulonephritis (1); glomerulopathy (1); heart failure (1); hemorrhage (1); Hyperglycemia (1); insulinoma (1); invasive breast carcinoma (1); myopathy (1); neutropenia (1); parasitemia (1); Progressive encephalopathy (1); tauopathies (1); Thromboembolism (1); Thrombosis (1).